Y_RNA (Y RNA )
Gene: Miscellaneous RNA gene on chromosome 6 (136,934,765 to 136,934,866, forward strand). Ensembl gene ENSG00000207247.
Homologues: Orthologues: chimpanzee Y_RNA (99% identical), macaque Y_RNA (95% identical). Paralogues in human: Y_RNA (90% identical), RNY3 (89% identical), Y_RNA (89% identical), RNY3P1 (88% identical), Y_RNA (88% identical), Y_RNA (87% identical), RNY3P14 (86% identical), Y_RNA (86% identical), Y_RNA (85% identical), Y_RNA (84% identical), RNY3P10 (83% identical), RNY3P11 (83% identical), and 93 more.